ZNF579 (zinc finger protein 579)
Description:
May be involved in transcriptional regulation.
Synonyms: FLJ35453
Tractability: PROTAC: ubiquitination databases record sites on it.
Gene: Protein-coding gene on chromosome 19 (55,576,774 to 55,580,916, reverse strand). Ensembl gene ENSG00000218891.
Subcellular location: Nucleus
Subcellular location (Human Protein Atlas): Nucleoplasm
Gene Ontology:
Molecular function: DNA-binding transcription factor activity, RNA polymerase II-specific; protein binding; RNA binding; transcription cis-regulatory region binding
Biological process: regulation of transcription by RNA polymerase II
Cellular component: nucleus
Genetic constraint (gnomAD): Loss-of-function variants: 3 observed, 2.41 expected, observed/expected ratio (o/e) 1.25, 90% interval 0.5 to 1.91. That is too few expected variants to judge how well the gene tolerates losing a copy. Missense variants: 679 observed, 550.47 expected, observed/expected ratio (o/e) 1.23, 90% interval 1.16 to 1.31. Synonymous variants: 454 observed, 285.01 expected, observed/expected ratio (o/e) 1.59, 90% interval 1.47 to 1.72.
Homologues: Orthologues: chimpanzee ZNF579 (100% identical), macaque ZNF579 (97% identical), dog ZNF579 (95% identical), pig ZNF579 (92% identical), rat Zfp579 (90% identical), mouse Zfp579 (89% identical), guinea pig ZNF579 (75% identical). Paralogues in human: ZNF668 (21% identical), ZNF850 (20% identical), PRDM5 (18% identical), ZNF358 (15% identical).
Diseases named in the same sentence as ZNF579 in open-access papers:
ZNF579 is named in the same sentence as 1 disease in open-access papers, as found by Europe PMC text mining. Sharing a sentence is not in itself a finding about the gene and the disease. The quoted sentences say what the papers report.
infection (1 paper, 2021). The state of being infected such as from the introduction of a foreign agent such as serum, vaccine, antigenic substance or organism. "The transcription factors GABPA, ZNF579, SP110, and TSC22D2 were also induced after infection." (PMID 34777295, 2021).